BRAF (B-Raf proto-oncogene, serine/threonine kinase)
Diseases named in the same sentence as BRAF in open-access papers (continued):
Sharing a sentence is not in itself a finding about the gene and the disease.
meningioma (11 papers, 2014 to 2026). A generally slow growing tumor attached to the dura mater. "BRAF mutations in meningiomas are relatively rare compared to other types of tumors, however, they can still occur." (PMID 38259646, 2023). "- Meningiomas: WT1- Hemangiomas: VEGFR2, Endoglin (CD105)- Melanocytic nevi: MART-1, BRAF, NRAS mutations- Lipoma: HMGA2-expressing cells." (PMID 40630962, 2025). "Indeed, it seems reasonable to assume that at least part of the meningioma cases previously believed to be caused by yet unrecognized genetic factors might in fact contain BRAF/NF2/PIK3CA/SMO mutations at frequencies inferior to the limits of traditional detection methods." (PMID 38259646, 2023). "Future investigations into the significance of BRAF fusions in meningioma may help select good candidates for targeted anti-BRAF therapy." (PMID 38066633, 2023). "The T cells in meningioma showed five additional drug-target kinases that were significantly increased in expression compared to VS (CSF1R, LYN, ABL, MAP2K1, and BRAF), whereas VS had only one drug-target kinase, KDR." (PMID 41437121, 2025). "The present study aimed to assess the occurrence of the mutations in the EGFR TK domain and in the selected downstream genes, KRAS, BRAF and PIK3CA, in a relatively large group of meningioma patients." (PMID 24932282, 2014). "In total, 55 formalin-fixed, paraffin-embedded meningioma samples were subjected to genomic sequencing of EGFR (exons 18–21), KRAS (exon 1), BRAF (exon 15) and PI3K (exons 9, 20)." (PMID 24932282, 2014). "However, BRAF fusions have not been recognized in meningioma." (PMID 38066633, 2023).
metastatic cancer (11 papers, 2017 to 2025). A carcinoma which has spread from the original site of growth to another anatomic site. "Current pleural effusion metastatic cancer cells showing BRAF mutation continue to be treated with dabrafenb and anlotinib; unfortunately, we did not perform PDL1 testing." (PMID 40502629, 2025). "The phase II “VE basket” trial evaluating the BRAF TKI vemurafenib in BRAF-mutated metastatic cancers showed mixed results with a response rate of 12% (one patient out of eight) in BRAF-mutated metastatic cholangiocarcinoma." (PMID 37760415, 2023). "Additionally, a study that analysed survival of KRAS and BRAF mutant metastatic cancers following complete liver resection found that there were comparable overall survival rates although fewer data for BRAF mutant cancers was available." (PMID 30598662, 2018).
non-Hodgkin lymphoma (11 papers, 2003 to 2025). Distinct from Hodgkin lymphoma both morphologically and biologically, non-Hodgkin lymphoma (NHL) is characterized by the absence of Reed-Sternberg cells, can occur at any age, and usually presents as a localized or generalized lymphadenopathy associated with fever and weight loss. "Conversely, germline variants in the BRAF gene rarely cause cancer, except in a few cases of acute lymphoblastic leukemia and non-Hodgkin’s lymphoma." (PMID 37697378, 2023). "As there have been no data on the BRAF mutation in non-Hodgkin's lymphoma (NHL), we analysed the genomic DNAs from 164 NHLs by polymerase chain reaction (PCR)-based single-strand conformation polymorphism (SSCP) for the detection of somatic mutations of BRAF (exons 11 and 15)." (PMID 14612909, 2003).
cyst (10 papers, 2017 to 2025). A sac-like closed membranous structure that may be empty or contain fluid or amorphous material. "The growth patterns were consistent in terms of cyst formation and solid growth from the 7th day onwards in both control and KRAS or BRAF mutated 3D cultures until the 10th day." (PMID 31545494, 2019). "Recent reports revealed that SMC have a median of 4 mutations per cyst, such as K-RAS and BRAF." (PMID 34619455, 2021).
esophageal cancer (10 papers, 2015 to 2025). A primary or metastatic malignant neoplasm involving the esophagus. "At present, the v-Raf murine sarcoma viral oncogene homolog B1 (BRAF) gene mutation has been observed in esophageal cancer and is associated with poor prognosis." (PMID 33622273, 2021). "Given that predictive markers for other epithelial cancers such as mutations in KRAS, EGFR or BRAF are rarely detected in esophageal cancers, EGFR expression has been predominantly investigated for its potentiality of predicting treatment outcome for esophageal cancers." (PMID 26124180, 2015). "We used immunohistochemistry to detect the expression of BRAF via tissue microarrays in esophageal cancer samples, the Kaplan–Meier method to perform survival analysis, and the Cox proportional hazards regression model to explore the risk factors of esophageal cancer." (PMID 33622273, 2021). "One prior study reported BRAF overexpression to be correlated with poorer survival in esophageal cancer, however, it is difficult to draw comparisons between this study and the present one." (PMID 40163685, 2025). "Survival analysis showed that BRAF overexpression contributed to a shorter overall survival (P = 0.014) in patients with esophageal cancer." (PMID 33622273, 2021). "Univariate and multivariate regression analyses demonstrated that BRAF was a prognostic factor for poor esophageal cancer outcomes (P < 0.05)." (PMID 33622273, 2021). "This study aimed to investigate the protein expression of BRAF in esophageal cancer and determine its effect on patient outcomes." (PMID 33622273, 2021). "In conclusion, our results suggested that BRAF overexpression correlated with lower overall survival in esophageal cancer patients." (PMID 33622273, 2021). "The role of BRAF in the proliferation, invasion, and metastasis of esophageal cancer was studied by clone formation, scratch test, Transwell invasion and migration test." (PMID 33622273, 2021). "In this study, we screened 64 ESCC tissue specimens for PD-L1 expression, HPV infection, MSI/dMMR, and mutations in the KRAS, BRAF, or PIK3CA genes to determine their prognostic value in esophageal cancers." (PMID 33054840, 2020). "However, MSI/dMMR, RAS/BRAF/PIK3CA mutations, and HPV status have been rarely investigated in esophageal cancers." (PMID 33054840, 2020). "In this study, PIK3CA mutation was detected in 12.5% of esophageal cancers and was associated with female or younger patients (≤60 years) lacking mutations in the KRAS and BRAF genes." (PMID 33054840, 2020).
liver cancer (10 papers, 2015 to 2025). An epithelial or non-epithelial malignant neoplasm that arises from the liver. "The RAS/RAF signaling pathway plays an essential role in the development of liver cancer, and BRAF is one of the essential cancer-associated genes in this pathway." (PMID 32449085, 2020). "It suggested that BRAF mutation could be an effective prognostic marker after surgical treatment of liver cancer." (PMID 28915706, 2017). "This system reduced the biological toxicity of CTAB on the surface of gold nanorods and showed high siRNA loading capacity and can be used to silence BRAF gene in liver cancer effectively." (PMID 32449085, 2020). "The novel nano-system GAL-GNR-siBRAF possesses three individual characteristics: specific targeting of liver cancer, siRNA-based gene silencing of BRAF, and GNR-offered photothermal effects." (PMID 32449085, 2020). "Treatment with GAL-GNR-siBRAF significantly downregulated the expression of BRAF and impaired proliferation, migration, and invasion of liver cancer cells." (PMID 32449085, 2020). "A recent clinical survey showed that BRAF (mutated RAF paralogue) mutation was associated with a poor median RFS (recurrence free survival rate), higher recurrence rate and mortality after hepatic cancer resection." (PMID 28915706, 2017). "The discovery of mutations in BRAF (B-Raf proto-oncogene, a serine/threonine kinase) and EGFR (epidermal growth factor receptor) by DNA sequencing contributed to the development of new targeted therapies for liver cancer patients carrying these mutations." (PMID 32280695, 2020). "At the same time, the combination of photothermal hyperthermia and BRAF gene silencing could cause more than 85% cell death which indicates that the synergy of GAL-GNR-siBRAF and photothermal effects could be an ideal strategy to inhibit liver cancer." (PMID 32449085, 2020). "In addition, the GAL-GNR-siBRAF simultaneously induced gene silencing of BRAF and photothermal effects which achieved synergistic efficacy in the killing ability of tumor cells, providing a new way of thinking for the development of clinical treatment of liver cancer." (PMID 32449085, 2020). "In this study, we designed a novel multifunctional nanomaterial GAL-GNR-siBRAF which consists of three parts, GAL as the liver cancer-targeting moiety, golden nanorods (GNR) offering photothermal capability under near infrared light, and siRNA specifically silencing BRAF (siBRAF)." (PMID 32449085, 2020).
mismatch repair deficiency (10 papers, 2012 to 2025). "The mechanism underlying the association between BRAF p.V600E and mismatch repair deficiency has not yet been established to our knowledge." (PMID 30412573, 2018).
myeloid neoplasm (10 papers, 2017 to 2026). Proliferation of myeloid cells originating from a primitive stem cell. "In myeloid neoplasms, BRAF mutations are rare, and their prevalence, molecular context, and clinical significance remain incompletely defined." (PMID 41898318, 2026). "Our study suggests that although BRAF mutations are rare in myeloid neoplasms, they play a crucial role in the pathogenesis of specific AML subtypes." (PMID 38791222, 2024). "It will be interesting to evaluate both HSPCs and lesional cells in RDD patients to assess for the presence of BRAF mutations as well as correlate the pattern of BRAF mutation involvement with clinical outcomes, especially the development of myeloid neoplasms." (PMID 39592527, 2024). "The purpose of our study is to characterize BRAF mutations in myeloid neoplasms using a next-generation sequencing (NGS) panel based on the experiences of a single cancer center." (PMID 38791222, 2024). "BRAF mutations are rare in myeloid neoplasms and are reported to be associated with poor treatment outcomes in patients with AML carrying BRAF mutations." (PMID 38791222, 2024). "BRAF mutations are rare in myeloid neoplasms and are reported to be associated with poor treatment outcomes." (PMID 38791222, 2024). "In our study, we found that BRAF mutations constitute 0.53% of myeloid neoplasms, consistent with previous studies reporting values from approximately 0% to 0.65%." (PMID 38791222, 2024). "The purpose of this study is to characterize the BRAF mutations in myeloid neoplasms using a multigene next-generation sequencing (NGS) assay based on the experiences of a single cancer center." (PMID 38791222, 2024). "Pathogenic or likely pathogenic BRAF mutations were identified in 14 patients, resulting in a prevalence of 0.53% (14/2632) in myeloid neoplasms." (PMID 38791222, 2024). "In this study, we utilized a comprehensive NGS panel to characterize the BRAF mutations and co-occurring mutations in myeloid neoplasms." (PMID 38791222, 2024). "Our study indicates that BRAF mutations are rare in myeloid neoplasms, constituting only 0.53% (14/2632) of all myeloid neoplasm cases, with the most common BRAF mutation being BRAF V600E (4/14; 28.6%)." (PMID 38791222, 2024). "Indeed, the identification of the BRAF mutation in this case aligns with the current understanding of LCH as a clonal myeloid neoplasm driven by activating mutations in the MAPK pathway." (PMID 41256912, 2025). "A total of 14 patients with myeloid neoplasms carrying BRAF mutations were included in our cohort." (PMID 38791222, 2024). "However, no comprehensive analysis has been conducted on the clinical and molecular characteristics of BRAF mutations in patients with myeloid neoplasms." (PMID 38791222, 2024). "Thus, our study indicates that although BRAF mutations are rare in myeloid neoplasms, constituting only 0.53% of cases in our cohort, they play a crucial role in the pathogenesis of specific AML subtypes." (PMID 38791222, 2024). "Importantly, elucidating the cytogenetic and molecular mechanisms that give rise to the evolution of BRAF-mutant myeloid neoplasms may enable the development of novel treatment approaches for patients." (PMID 39596583, 2024). "However, the significance of BRAF mutations in myeloid neoplasms has not been widely investigated." (PMID 38791222, 2024).
neuroendocrine carcinoma (10 papers, 2017 to 2026). A malignant neuroendocrine neoplasm composed of cells containing secretory granules that stain positive for NSE and chromogranin. "The increased prevalence of the BRAF V600E mutation in partially neuroendocrine cancers may identify a new subpopulation eligible for BRAF inhibition." (PMID 37240418, 2023). "Similarly, a patient with neuroendocrine cancer of the bowel was found to have an activating mutation of BRAF (p.V600E) and became eligible for a RAF inhibitor clinical trial." (PMID 29100271, 2017). "There are occasional case reports of targeted treatment of BRAF V600E mutated pancNETs as well as poorly differentiated neuroendocrine carcinoma (NEC) of GI origin with varying results; however, this is the first report of D/T treatment specific to NET G3 of pancreatic origin." (PMID 38814411, 2024). "Other studies confirmed the frequent BRAF mutations in these tumors; interestingly, the dramatic response to BRAF-MEK combination therapy was observed in two cases of metastatic high-grade neuroendocrine carcinoma refractory to standard therapy and displaying BRAF (V600E) mutation." (PMID 29652830, 2018).
Pleural effusion (10 papers, 2018 to 2025). The presence of an excessive amount of fluid in the pleural cavity. "Subsequent next‐generation sequencing of genetic material from metastatic tumor cells from a malignant pleural effusion revealed a BRAF V600E mutation, corroborating the ctDNA testing result." (PMID 30113761, 2018). "In parallel, the ctDNA analysis, performed on both plasma and pleural effusion, detected a rebound of the BRAF MAF." (PMID 37569660, 2023). "The third TNBC patient with a BRAF V600E mutation was a 57-year-old woman with metastatic TNBC and chemotherapy-refractory massive pleural effusion." (PMID 36011019, 2022). "As next we evaluated our targeted EGFR, KRAS and BRAF test results from cfDNA obtained from pleural effusion and blood and from gDNA isolated from sediment cell blocks and lung biopsies." (PMID 34257581, 2021). "We established a novel cell line (PF49) from the malignant pleural effusion of a 68-year-old male patient with ATC that rapidly transformed from a BRAF and TERT promoter mutant PTC." (PMID 32591993, 2020). "Detection of BRAF p.V600E (VAF of 49%), NRAS p.Q61K (VAF of 19%) and NRAS p.Q61 (VAF of 3.3%) in this pleural effusion specimen are consistent with two NRAS-mutated resistant subclones emerging following targeted therapy." (PMID 31277584, 2019).
renal carcinoma (10 papers, 2011 to 2025). A carcinoma arising from the epithelium of the renal parenchyma or the renal pelvis. "Although the morphological features were similar between MA and the other eight renal carcinoma cases which were initially misdiagnosed in this study, none of these renal carcinoma cases showed a BRAF exon 15 mutation (data not shown)." (PMID 30111351, 2018).
acute lymphoblastic leukemia (9 papers, 2011 to 2023). Leukemia with an acute onset, characterized by the presence of lymphoblasts in the bone marrow and the peripheral blood. "The rare BRAF L597Q (c.T1790A) point mutation has been previously reported in childhood acute lymphoblastic leukemia." (PMID 33578538, 2021). "Conversely, the prevalence of BRAF V600E mutation in chronic and acute leukemias ranges between 0 and 10% with only Gustafsson demonstrated that 20.7% of acute lymphoblastic leukemia (ALL) had BRAF V600E mutations." (PMID 27738305, 2017). "SF3B1 combined with BRAF mutation might contribute to the development of acute lymphoblastic leukemia." (PMID 32143579, 2020). "Mutations in FLT3, KRAS, NRAS, and BRAF genes have been observed with variable prevalence (5-20%) in acute myeloid (AML) and lymphoblastic leukaemias (ALL)." (PMID 24571676, 2014). "As has been recently shown in acute lymphocytic leukaemia, it is speculated that precancerous melanocytes already harbouring an unknown first hit may subsequently acquire multiple driver mutations; thus, the acquisition of BRAF mutation might be one of these secondary events." (PMID 21224857, 2011). "Nevertheless, it remains to be evaluated whether the assessment of BRAF levels at certain time points of therapy might help to stratify the intensity of treatment as it has been shown for minimal residual disease in acute lymphoblastic leukemia." (PMID 29774135, 2018).
cervical carcinoma (9 papers, 2015 to 2024). A carcinoma arising from either the exocervical squamous epithelium or the endocervical glandular epithelium. "Tian et al30 identified that the cervical cancer patients with five notable nonsynonymous mutant genes (PIK3CA, BRAF, GNA11, FBXW7, and CDH1) metastatic relapse significantly mutated mutations had significantly poor DFS and OS." (PMID 35762423, 2023).
Costello syndrome (9 papers, 2007 to 2024). "Among this group of disorders, craniosynostosis appears to be consistently associated with Noonan, CFC, and Costello syndromes with pathogenic variants most frequently reported in BRAF, HRAS, KRAS, and PTPN11." (PMID 37774117, 2024). "Germline mutations in BRAF were previously associated with cardiofaciocutaneous, Noonan, and Costello syndromes." (PMID 32858845, 2020). "Costello syndrome is caused by mutations in HRAS, NF1 by mutations in Neurofibromin and CFC syndrome by mutations in BRAF, KRAS and MEK1/2." (PMID 17222357, 2007). "The remaining genes involved were RAF1 (three patients, all with Costello syndrome suspicion), RIT1 (two patients), BRAF (one patient), MAP2K1 (three patients), MAP2K2 (two patients), PTPN11 (two patients), SOS1 (one patient), and SHOC2 (three patients, two of them with Costello syndrome suspicion)." (PMID 37568403, 2023).
diffuse midline glioma (9 papers, 2017 to 2025). A diffuse glioma that arises from the midline structures of the central nervous system. "Accounting for all these differences, they propose the new category of diffuse midline glioma, H3K27 and BRAF/FGFR1 co-altered." (PMID 39126064, 2024).
LEOPARD syndrome (9 papers, 2011 to 2025). "BRAF mutations are typically somatic mutations, but germline mutations can cause congenital syndromes like cardio‐facio‐cutaneous (CFC), Noonan, and Leopard syndromes." (PMID 39950095, 2025). "We also report more detailed functional analyses of the less well characterised BRAF p.T241P and BRAF p.G469E mutants, which occur in both Leopard syndrome and CFC25,27,28." (PMID 33795686, 2021). "BRAF and RAF1 are two functionally-related paralogous genes of the RAF family of serine/threonine protein kinases, known to be causal for various types of Noonan and Leopard syndromes." (PMID 29723191, 2018).